RPL23AP2 (ribosomal protein L23a pseudogene 2)
Gene: Transcribed processed pseudogene on chromosome 19 (15,611,657 to 15,612,122, forward strand). Ensembl gene ENSG00000225067.
Diseases named in the same sentence as RPL23AP2 in open-access papers:
RPL23AP2 is named in the same sentence as 1 disease in open-access papers, as found by Europe PMC text mining. Sharing a sentence is not in itself a finding about the gene and the disease. The quoted sentences say what the papers report.
breast carcinoma (1 paper, 2021). "Three common lncRNAs were identified to be significantly differentially expressed and co‐expressed with the breast cancer genes, which include RP11‐108F13.2, RPL23AP2 and AL022324.2." (PMID 33991433, 2021).